LINC01766 (long independently transcribed non-coding RNA 1766)
Gene: Long non-coding RNA gene on chromosome 19 (35,557,656 to 35,601,596, forward strand). Ensembl gene ENSG00000224910.
Gene Ontology:
Molecular function: structural constituent of ribosome; triplet codon-amino acid adaptor activity
Biological process: translation
Cellular component: ribosome